FBN1 (fibrillin 1)
Diseases named in the same sentence as FBN1 in open-access papers (continued):
Sharing a sentence is not in itself a finding about the gene and the disease.
Obesity (10 papers, 2016 to 2025). Accumulation of substantial excess body fat. "In the ANS/inflammation-induced obesity network, the fibrilin 1 (FBN1) gene, encoding the asprosin hormone, interacts only with IL6, which, in turn, interacts with interferon gamma (IFNG)." (PMID 39062927, 2024). "This discovery is consistent with the correlation between FBN1 expression and obesity and provides a mechanism for the association between fibrillin-1 and body fat." (PMID 27386756, 2016). "However, the role of elastin and fibrillin-1 in obesity and obesity-associated cancer progression remains to be investigated." (PMID 36428776, 2022). "More interestingly, FBN1 interacts directly with IFNG in stress-induced obesity but with IL6 in ANS/inflammation-induced obesity." (PMID 39062927, 2024). "The fibrilin 1 (FBN1) gene, which encodes the asprosin hormone, interacts only with IGFBP1 in the stress-induced obesity network." (PMID 39062927, 2024). "The FBN1 gene was significantly correlated with a profile of adiposity, glucose, and insulin metabolism, even after adjusting for age in the obesity-induced T2DM." (PMID 35462799, 2022). "Furthermore, asprosin, a glucogenic adipokine derived from fibrillin‐1 (FBN1), promotes hepatic glucose release and is elevated in metabolic disorders (e.g., obesity, insulin resistance)." (PMID 40515432, 2025). "It has been reported that FBN1 can initiate the development of obesity-induced diabetes." (PMID 36118693, 2022). "THBS1 is required for this shift, since the expression of numerous obesity-induced, ECM-related FAP genes (such as Fbn1, Col3a1, and Adamts5) is markedly blunted in HFD-fed KO mice." (PMID 38954467, 2024). "Therefore, we investigated the relation of Fibrilln-1 (FBN1) mRNA expression and hepatic phosphoenolpyruvate caboxykinase (PEPCK) enzyme to the ameliorative impact of oxytocin on obesity-induced diabetes, suggesting glycogenolysis markers in diabetic models." (PMID 35462799, 2022). "Therefore, oxytocin has a potential effect on FBN1 expression and PEPCK enzyme activity in the obesity-induced diabetic-rat model." (PMID 35462799, 2022). "In contrast, the adipogenesis genes COL12A1, FBN1 and RBP4, as well as the genes CASP6 and DPT that involved in inflammation or immune response, were downregulated in obese pigs but upregulated in obese human, consistent with previous reports showing their upregulation in obesity." (PMID 40658709, 2025). "Our interactomes elucidate novel interactions of FBN1, through which non-hereditary types of obesity may result." (PMID 39062927, 2024).
systemic sclerosis (10 papers, 2005 to 2024). A chronic disorder, possibly autoimmune, marked by excessive production of collagen which results in hardening and thickening of body tissues. "The inhibition of mTOR cascade by rapamycin ameliorates the osteopenia phenotype in Fbn1+/− systemic sclerosis (SSc) mice." (PMID 38269088, 2023). "For example, it has been revealed that microfibrils isolated from the skin of Tsk-/- mice, a model of systemic sclerosis, are enriched in FBN1 and promote a prooxidant phenotype in cultured endothelial cells which contributes to the mesenchymal transition." (PMID 34440261, 2021). "Screening of fibrillin-1 antibodies was performed in 41 sera from systemic sclerosis patients and in 44 healthy controls with a Caucasian background." (PMID 16277674, 2005). "Autoantibodies against short recombinant fragments of fibrillin-1 produced in bacterial expression systems have been found in tight-skin mouse, systemic sclerosis, mixed connective tissue disease, and primary pulmonary hypertension syndrome." (PMID 16277674, 2005). "While the FBN-1/TGF-β may play a major role in systemic sclerosis, such a complex may be also a major feature of fibrillinopathies." (PMID 39596376, 2024). "Given the association between aberrant expression of TGF-β, that also serves as a pro-inflammatory cytokine, and radiation-induced fibrosis, patients with FBN1 abnormalities, like those suffering from MFS and some systemic scleroderma, exhibit high susceptibility to radiation-induced (RI) fibrosis." (PMID 39596376, 2024). "Mice with an RGE knock-in within TB4 of FBN1 develop a phenotype of systemic scleroderma." (PMID 38269088, 2023). "Alterations in fibrillin-1 have been reported in patients with systemic sclerosis (SSc, or scleroderma) and in the tight skin 1 (Tsk1) mouse model." (PMID 23962393, 2013). "The analysis of 41 sera from Caucasian patients with systemic sclerosis showed that none of the sera exceeded the cutoff value for the N-terminal half of fibrillin-1." (PMID 16277674, 2005). "The data show the absence of autoantibodies against recombinant fibrillin-1 protein in Caucasian systemic sclerosis patients." (PMID 16277674, 2005). "ELISAs showed that none of the sera of patients with systemic sclerosis contained autoantibodies against the N-terminal or C-terminal recombinant fibrillin-1 polypeptide." (PMID 16277674, 2005).
lipodystrophy (8 papers, 2014 to 2024). A congenital or acquired disorder characterized by abnormal loss or redistribution of the adipose tissue in the body. "Examination of the FBN1 gene showed that the region commonly affected in FBN1-associated lipodystrophy is highly conserved both across the three human fibrillin genes and across genes encoding fibrillin-1 in vertebrates." (PMID 27386756, 2016). "Coding Exon 64 of the FBN1 gene is important for the role of fibrillin-1 in human adipose tissue, since individuals with mutations truncating the protein at this point have severe lipodystrophy." (PMID 27386756, 2016). "In addition it would be valuable to record measures of body fat status of patients with FBN1 mutations, so that the mutations which predispose to lipodystrophy can be further characterised." (PMID 27386756, 2016). "Since the C-terminal peptide of fibrillin-1 is a glucogenic hormone, individuals with low fibrillin-1 (for example with FBN1 mutations associated with lipodystrophy) may fail to differentiate adipocytes and/or to accumulate adipocyte lipids, although this still needs to be shown experimentally." (PMID 27386756, 2016). "Another very rare, particular, and early onset phenotype related to FBN1 variants specifically located in exon 64 occurs in a progeroid disease known as MPLS, which comprises lipodystrophy and partial manifestations of MFS." (PMID 38667733, 2024). "The C-terminus of fibrillin-1, which contains a glucogenic hormone, correlates with lipodystrophy in MPL patients." (PMID 29666143, 2018). "Our results also confirmed a significant decrease in blood glucose levels and lipodystrophy in the FBN1 Het rabbits." (PMID 29666143, 2018). "Owing to a truncated C-terminus of fibrillin-1, new phenotypes of lipodystrophy and progeroid appearance were also seen in the MPL rabbit model." (PMID 29666143, 2018). "A highly conserved region of the C-terminus of FBN1 was speculated to be related to congenital lipodystrophy in humans." (PMID 29666143, 2018). "Extreme cases of lipodystrophy with or without Marfanoid features have been associated with mutations at the 3′ end of the FBN1 gene." (PMID 27386756, 2016). "The peptide beyond the furin cleavage site, which would be absent in the lipodystrophy patients, is also essential for the secretion of fibrillin-1; for some patients proteins lacking the C terminal amino acids were retained within the cell." (PMID 27386756, 2016). "Moreover, skin symptoms, lipodystrophy, growth retardation and dysglycemia were also seen in these FBN1 Het rabbits, and have not been reported in other animal models." (PMID 29666143, 2018).
scleroderma (8 papers, 2005 to 2023). Scleroderma is a rare autoimmune connective tissue disorder characterized by abnormal hardening of the skin and, sometimes, other organs. "This situation has rapidly changed because new evidence from acquired and congenital forms of human scleroderma and Tsk/+ mice has implicated dysfunction of fibrillin-1 microfibrils in skin fibrosis." (PMID 21126338, 2010). "Recently, abnormal FBN-1 has been hypothesized to be the cause aberrant TGF-β signaling in scleroderma." (PMID 19025617, 2008). "Additionally, the study of congenital dysfunctions of fibrillin-1 has yielded insights into the pathogenesis of acquired connective tissue disorders of the connective tissue, such as scleroderma." (PMID 21126338, 2010). "In patients with scleroderma, the frequency of anti-fibrillin-1 antibodies was 42% in Caucasians." (PMID 16277674, 2005). "FBN1 expression is increased in scleroderma skin, which is unusually degradation-susceptible, and the presence of anti-fibrillin-1 antibodies in SSc is thought to activate fibroblasts and stimulate the release of TGF-β, all supportive of FBN1′s potential role in scleroderma pathogenesis." (PMID 37372943, 2023). "It seems that an altered FBN-1/TGF-β pathway is common to pathogenesis MFS, scleroderma and TSK mouse." (PMID 19025617, 2008). "Besides, α‐smooth muscle actin (αSMA), Fibulin 1 (FBN1), and vimentin (VIM) which are often used to identify pathologic fibroblasts and myofibroblasts were highly expressed in the dermis of scleroderma skin, compared to the control group." (PMID 35315234, 2022). "SSS mutations cluster around the sole integrin-binding RGD sequence of fibrillin-1, and lead to a highly restricted (as opposed to a systemic) phenotype that resembles a congenital form of scleroderma." (PMID 21126338, 2010).
dilated cardiomyopathy (7 papers, 2020 to 2025). Cardiomyopathy which is characterized by dilation and contractile dysfunction of the left and right ventricles. "Fibrillin 1-deficient mice show dilated cardiomyopathy directly related to the reduced expression of fibrillin 1, accompanied by increased expression of angiotensin II type 1 receptor (AT1R) and reduced focal adhesion kinase (FAK) activity." (PMID 40274989, 2025). "Although pathogenic variants in FBN1 are associated with an increased risk for dilated cardiomyopathy in both patients and mice, FBN1 is expressed in many tissues, including SMCs, cardiomyocytes, and cardiac fibroblasts." (PMID 39185210, 2024). "Fbn1-deficient mice demonstrate dilated cardiomyopathy, thus altering physical properties and chronic mechanical stress with reduced elasticity and increased ERK1/2 and pERK1/2." (PMID 38461168, 2024). "The authors suggested that fibrillin-1 is implicated in the physiological adaptation of the myocardium to an increased workload and that dilated cardiomyopathy is a primary manifestation of MFS mice." (PMID 32992882, 2020).
neonatal progeroid syndrome (7 papers, 2013 to 2025). "Wiedemann-Rautenstrauch Syndrome is a heterogeneous disorder caused by a pathogenic variant found in one of a few genes, including POLR3A, FBN1, CAV1, and SLC25A24." (PMID 40440483, 2025). "Its discovery stemmed from investigations into neonatal progeroid syndrome (NPS), a rare genetic disorder associated with FBN1 mutations, leading to aberrant asprosin processing and secretion." (PMID 39057043, 2024). "Studies of patients with Neonatal Progeroid Syndrome (NPS), caused by mutations in the FBN1 gene, show a deficiency of plasma ASP, resulting in extreme emaciation and fat deficiency." (PMID 36235674, 2022).
endothelial dysfunction (6 papers, 2010 to 2025). In vascular diseases, endothelial dysfunction is a systemic pathological state of the endothelium (the inner lining of blood vessels) and can be broadly defined as an imbalance between vasodilating and vasoconstricting substances produced by (or acting on) the endothelium. "Clinical studies of MFS patients associated a fibrillin-1 deficiency with endothelial dysfunction in the brachial artery." (PMID 35163812, 2022). "The heterozygous TSK-1 mouse, which carries a 30- to 40-kb genomic duplication in the fibrillin-1 gene, has marked hyperplasia of loose connective tissue around the thoracic aorta and altered aortic hemodynamics ex vivo suggestive of endothelial dysfunction." (PMID 20398328, 2010). "We hypothesis that the reduction of fibrillin-1 expression and the loss of integrity of the IEL brings about complex multifactorial changes to fibrillin-1 associated proteins involved in cell adhesion and leads to the endothelial dysfunction observed in MFS." (PMID 40695874, 2025).
geleophysic dysplasia 2 (6 papers, 2016 to 2024). Any geleophysic dysplasia in which the cause of the disease is a mutation in the FBN1 gene. "The same phenotype can be caused by monoallelic variants in FBN1 (encoding fibrillin 1) or LTBP3 (encoding latent transforming growth factor-beta-binding protein 3), which are referred to as geleophysic dysplasia type 2 (GD2) and type 3 (GD3), respectively." (PMID 38300707, 2024).
papillary thyroid carcinoma (6 papers, 2018 to 2023). "FBN1 is also closely associated with papillary thyroid carcinoma." (PMID 38269088, 2023). "It is highly expressed in papillary thyroid carcinoma, and silencing of FBN1 inhibits cell viability and colony formation in vitro and inhibits tumor growth in vivo." (PMID 38269088, 2023). "FBN1 silencing leads to decreased papillary thyroid carcinoma cell proliferation and enhances apoptosis in vitro, up-regulation of FBN1 boosts xenograft tumor formation in vivo." (PMID 29740513, 2018).
adenoma (5 papers, 2004 to 2025). A neoplasm arising from the epithelium. "We had for the first time studied FBN1 methylation risk from controls to CRC through adenoma or polyp." (PMID 35515111, 2022). "The incidences of 10.8%, 50.7%, and 74.6% of FBN1 methylation from healthy control to CRC though adenoma or polyp in feces were gradually increasing; this increasing risk size was closely related to the histological process of CRC evolution." (PMID 35515111, 2022). "In the samples of tissue colorectal cells, we used similar methods as above; the incidence of FBN1 methylation in the corresponding control, adenoma or polyp, and CRC was 2%, 69.4%, and 79.1%, respectively." (PMID 35515111, 2022). "We had found that FBN1 methylation incidence of control, adenoma or polyp patients, and CRC in tissue was 2.7%, 69.4%, and 79.1%, respectively, and that in feces it was 10.8%, 50.7%, and 74.6%, respectively." (PMID 35515111, 2022). "Among the adenomas, INA and FBN1 methylation was more frequently found in large (10 mm or larger) than in small adenomas (smaller than 10 mm in diameter; P = 0.012 and P = 0.047, respectively; T-test)." (PMID 21777459, 2011). "In focal nodular hyperplasia, fibrillin-1 was more strongly expressed in the perisinusoidal space, compared with surrounding liver; in contrast, in adenomas fibrillin-1 immunostaining was irregular and very low in perisinusoidal space, more intense in peliotic areas." (PMID 14960209, 2004). "FBN1 methylation frequencies of CRC, adenoma or polyp, and control in tissue were 79.1%, 69.4%, and 2.7%, respectively; those in feces were 74.6%, 50.7%, and 10.8%, respectively." (PMID 35515111, 2022). "Within 60 adenoma samples (median age 67 years) successfully amplified by qMSP, promoter hypermethylation was detected in 90%, 68%, 42%, 85% and 55% for CNRIP1, FBN1, INA, MAL, and SNCA, respectively, and 90% of the adenomas harbored co-methylation." (PMID 21777459, 2011).
ascending aortic aneurysm (5 papers, 2014 to 2022). "For example, mutations in the gene encoding fibrillin-1 can cause progressive ascending aortic dilatation." (PMID 36588574, 2022). "Finally, the 2 patients bearing FBN1 mutations had significant aortic regurgitation, which is a powerful predictor of loss of aortic medial elastic fibers in patients with ascending aortic aneurysms and aortic valve disease." (PMID 24564502, 2014).
atherosclerosis (5 papers, 2017 to 2024). A disease characterized by the build-up of fatty material and calcium deposition in the arterial wall resulting in partial or complete occlusion of the arterial lumen. "Researchers reported that the cross-breeding of ApoE-/- mice with mice having a heterozygous mutation (C1039G+/-) in the fibrillin-1 (Fbn1) gene revealed the effect of altered elastin structure of the arterial wall on the advancement of atherosclerosis." (PMID 38629090, 2024). "An association with the pathogenesis of atherosclerosis has been shown for circulating complement C3, and with acute myocardial infarction for titin and fibrillin-1." (PMID 28273075, 2017). "FBN1 variant (C1039G (+/-)) can also promote atherogenesis and a highly unstable plaque phenotype in apolipoprotein E-deficient (ApoE (-/-)) mice model of atherosclerosis." (PMID 38715006, 2024). "In apolipoprotein E-deficient mice with a heterozygous mutation in the fibrillin-1 gene (ApoE−/−Fbn1C1039G+/−), a model of advanced atherosclerosis, statins do not lower cholesterol." (PMID 34684024, 2021). "In apolipoprotein E-deficient mice with a heterozygous mutation in the fibrillin-1 gene (ApoE−/−Fbn1C1039G+/−) on a Western diet (WD)—a model of advanced atherosclerosis—statins do not significantly lower cholesterol." (PMID 34684024, 2021).
dolichostenomelia (5 papers, 2015 to 2024). "Mutations of the FBN1 gene encoding fibrillin-1 are the most common genetic cause of Marfanoid habitus, and FBN1 mutations can be detected in >90% of individuals with classic MFS." (PMID 36421783, 2022). "Because additional genes are associated with Marfanoid habitus, the FBN1 gene cannot be considered a unique genetic cause of Marfanoid habitus." (PMID 36421783, 2022).
hereditary disorder of connective tissue (5 papers, 2019 to 2024). An inherited genetic disorder that affects the connective tissues. "The fact that a MASS-like phenotype was considered in our clinically different patients may suggest that the diagnosis of MASS is applicable not only to FBN1-related disorders, but also to other hereditary disorders of connective tissue." (PMID 35296718, 2022).
MASS syndrome (5 papers, 2016 to 2024). A genetic disorder of connective tissue caused by mutations in the FBN1 gene. "A peculiar aspect of this study was the inclusion of four different phenotypes of the same genetic disorder, FBN1 gene mutation: MLSF, MVPS, MASS syndrome, and MS." (PMID 39459359, 2024). "A recent study reported two FBN1 deep intronic variants ([c.6872-24T>A] and [c.7571-12T>A]) in two unrelated patients who were affected with MFS/aortic disease and MASS syndrome, respectively." (PMID 36675070, 2023). "Here, we report two unrelated individuals with the FBN1 deep intronic variants c.6872-24T>A and c.7571-12T>A, clinically associated with MFS and MASS syndrome, respectively." (PMID 31185693, 2019).
neonatal Marfan syndrome (5 papers, 2012 to 2024). "Neonatal Marfan syndrome (nMFS) is a rare condition characterized by severe phenotype and poor prognosis, caused by mutations in the specific “neonatal region” of the fibrillin 1 gene (FBN1)." (PMID 39294662, 2024).
prostate carcinoma (5 papers, 2011 to 2022). A carcinoma that arises from epithelial cells of the prostate gland. "FBN1 methylation has previously been identified in prostate cancer cell lines and the gene has also been shown to be epigenetically silenced in tumor endothelial cells." (PMID 21777459, 2011). "Quantitative methylation analyses have recently reported that the promoter of Fbn1 was hypermethylated in colorectal and prostate cancers in comparison to normal tissues, suggesting that this gene could play a role in oncogenesis." (PMID 23593401, 2013). "We also identified biomarkers, namely, ITGB1, FBN1, and THBS1, secreted by BC cells constituting lesions of all grades as well as the examined adenocarcinomas (colorectal, gastric, hepatocellular, melanoma, non-small cell lung cancer, ovarian, pancreatic, and prostate cancer)." (PMID 36010848, 2022).